WNT5A (Wnt family member 5A)
Diseases named in the same sentence as WNT5A in open-access papers (continued):
Sharing a sentence is not in itself a finding about the gene and the disease.
osteosarcoma (continued). "We have reported that the phosphatidylinositol-3 kinase (PI3K)/Akt/RhoA signaling pathway mediates Wnt5a-induced cell migration of osteosarcoma cells." (PMID 29213214, 2017). "Our previous study illuminates that Wnt5a mediates the migration of osteosarcoma cells via elevating the phosphatidylinositol-3 kinase (PI3K)/Akt and RhoA signaling." (PMID 29213214, 2017). "Specific inhibitors targeting PI3K and Akt retard Wnt5a-induced cell migration in ROR2-overexpressed osteosarcoma cells." (PMID 29213214, 2017). "WNT5A expression was found to increase in some osteosarcomas and to promote migration and invasion of this cancer type." (PMID 26978652, 2016). "To determine if the reduction in promoter B transcript levels is a characteristic of osteosarcoma tumor tissue, we measured WNT5A promoter A and B transcript levels in osteosarcoma tissue from three individual patients." (PMID 26978652, 2016). "Cancers in which WNT5A is typically upregulated include melanoma, gastric, skin, pancreatic, and osteosarcoma." (PMID 26978652, 2016). "Our results show that the WNT5A alternative promoters A and B are differentially expressed in both osteosarcoma cell lines SaOS-2 and U2OS and patient osteosarcoma tumor tissues." (PMID 26978652, 2016). "It is reported that Wnt5a signaling is involved in the regulation of osteosarcoma cell invasiveness." (PMID 26080812, 2015). "In summary, we present the first direct evidence here that Wnt5a promotes osteosarcoma cell migration via PI3K/Akt signaling." (PMID 24524196, 2014). "In this study, we demonstrated that Wnt5a promoted MG-63 osteosarcoma cell migration by activating PI3K/Akt." (PMID 24524196, 2014). "The first observation in the present study was that Wnt5a induced the migration of MG-63 osteosarcoma cells." (PMID 24524196, 2014). "Ten years ago, from 600 cDNA microarray experiments of human osteosarcoma cell lines, five genes (Axl, TGFA, COLL7A1, WNT5A, and MKK6) have been identified and were associated with adherence, motility, and/or invasiveness of cancer cells." (PMID 24599309, 2014). "In this study, we found that Wnt5a stimulated the migration of human osteosarcoma cells (MG-63), with the maximal effect at 100 ng/ml, via enhancing phosphorylation of phosphatidylinositol-3 kinase (PI3K)/Akt." (PMID 24524196, 2014). "To assess the effect of Wnt5a on osteosarcoma cell migration, we treated MG-63 cells with different doses of recombinant Wnt5a (rWnt5a), and measured the migration rate by wound healing assays and Boyden chamber assays." (PMID 24524196, 2014). "In this study, we have showed that Wnt5a promotes cell migration of human osteosarcoma cells in the PI3K/Akt-dependent manner." (PMID 24524196, 2014). "Taken together, we demonstrated for the first time that Wnt5a promoted osteosarcoma cell migration via the PI3K/Akt signaling pathway." (PMID 24524196, 2014). "FHL2 silencing also decreased the expression of c-Myc, which is involved in cell proliferation, and Wnt5a and Wnt10b, which are involved in osteosarcoma severity and invasiveness." (PMID 23383046, 2013). "Thus, loss of WNT5A expression may be a key event in malignant transformation in osteosarcoma." (PMID 19888226, 2009). "As in CRC, the different isoforms of WNT5A have different roles in osteosarcoma cell lines." (PMID 34017835, 2021). "Specifically, WNT5A increased migration and invasion of osteosarcoma cell lines." (PMID 34017835, 2021). "Thus, 100 ng/mL Wnt5a was used in study to identify the mechanism whereby changes in the migration of osteosarcoma cells were induced." (PMID 28289332, 2017). "It is still largely unknown which isoforms of PI3Ks and Akts regulate the Wnt5a-induced migration of osteosarcoma cells." (PMID 28289332, 2017). "Here, PI3Kα, PI3Kβ, Akt1 and Akt2 isoforms regulate Wnt5a-induced osteosarcoma cell migration." (PMID 28289332, 2017). "However, the signaling pathways regulating Wnt5a/PI3K/Akt-mediated cell migration remains poorly defined in osteosarcoma cells." (PMID 28289332, 2017).
osteosarcoma (continued). "We also used dominant-negative constructs (DN-RhoA) to knock down RhoA expression in osteosarcoma cells and checked whether Wnt5a-induced cell migration could be inhibited." (PMID 28289332, 2017). "Here, we demonstrate that ROR2 mediates Wnt5a-induced cell migration of osteosarcoma." (PMID 29213214, 2017). "We determined that inactivation of promoter B in the osteosarcoma cell lines involves DNA methylation but also includes histone modifications, supporting the conclusion that the WNT5A alternative promoters are differentially regulated by epigenetic mechanisms in osteosarcoma tumors." (PMID 26978652, 2016). "Nothing is known regarding the activities of the WNT5A promoters A and B in osteosarcoma cancers." (PMID 26978652, 2016). "In this study, we hypothesized that the PI3K/Akt signaling pathway might mediate Wnt5a-induced osteosarcoma cell migration." (PMID 24524196, 2014). "Our finding suggest that Wnt5a acts as a migratory stimulator in osteosarcoma cells." (PMID 24524196, 2014). "Furthermore Wnt5a showed an increase while its antagonist sFRP2 decreased in Snail2 overexpressing osteosarcoma cells compared to controls." (PMID 23352643, 2013). "ROR2 is a receptor tyrosine kinase involved in WNT-5a signaling, has been described as a prognostic biomarker as well as a potential therapeutic target in gastrointestinal stromal tumors and leiomyosarcomas, and its expression correlates with disease severity in osteosarcoma." (PMID 36508875, 2023). "Although there are substantial evidences given that Wnt5a binds to diverse receptors and promotes cellular behaviors (e.g. cell chemotaxis, cell proliferation), it is still much uncertainty regarding the receptor responds to Wnt5a and regulates metastatic behavior of osteosarcoma cells." (PMID 29213214, 2017). "Thus, RhoA activation is regulated by Wnt5a signaling in MG-63 osteosarcoma cells." (PMID 28289332, 2017). "Thus, ROR2 participates in Wnt5a-induced osteosarcoma cell migration." (PMID 29213214, 2017). "However, there is still unknown which receptors responds to Wnt5a signaling and participates in osteosarcoma metastasis." (PMID 29213214, 2017). "Wnt5a-triggered signals in human osteosarcoma cells have remained completely unknown." (PMID 24524196, 2014). "However, Wnt5a signaling in osteosarcoma progression remains poorly defined." (PMID 24524196, 2014). "The expression profiles of six core genes (WNT5A, GCA, ANXA6, BIRC5, IL1β, and ARPC3) were contrasted between the control and osteosarcoma groups." (PMID 40616392, 2025). "For instance, WNT5A promotes MMP‐14 expression and cell motility in human osteosarcoma cells via the ERK pathway." (PMID 39466654, 2024). "Human osteosarcoma cells, pretreated with 10 μmol/L LY294002 (PI3K inhibitor) for 1 h, were incubated with 100 ng/mL of Wnt5a." (PMID 28289332, 2017). "Here, we transfected osteosarcoma MG-63 cells with ROR2-Flag or stable ROR2 knockdown MG-63 cells, then were incubated with 100 ng/mL of Wnt5a and subjected to clonogenic assays." (PMID 29213214, 2017). "In this study, we demonstrated that RhoA activation acts as the downstream of Wnt5a/PI3K/Akt signaling, and is specifically regulated by PI3Kα, Akt1 and Akt2 isoforms in osteosarcoma cells." (PMID 28289332, 2017). "In the previous study, we have found that Wnt5a induces the migration of MG-63 osteosarcoma cells by triggering PI3K/Akt signaling, suggesting that Wnt5a acts as a migratory stimulator in osteosarcoma cells." (PMID 28289332, 2017). "In this study, we analyzed expression from two of the major WNT5A promoters, termed promoter A and promoter B, in normal human osteoblasts, SaOS-2 and U2OS osteosarcoma cell lines, and osteosarcoma tumor tissue." (PMID 26978652, 2016). "The levels of WNT5A promoters A and B transcripts were quantified in RNA from normal osteoblasts, osteosarcoma cell lines U2OS and SaOS-2, and osteosarcoma tumor tissue from three different individuals." (PMID 26978652, 2016).
osteosarcoma (continued). "Human osteosarcoma cells, serum-starved for 24 h and pretreated with 20 μM LY294002 for 1 h, were incubated with 100 ng/ml of Wnt5a." (PMID 24524196, 2014). "In osteosarcoma cells, suppressed expression of ROR2 (or its extracellular effector, WNT5A) inhibits cell invasiveness and decreases invadopodium formation." (PMID 20591152, 2010). "Other genes, including WNT5A (AUC = 0.935), GCA (AUC = 0.922), ANXA6 (AUC = 0.909), ARPC3 (AUC = 0.909), and IL1β (AUC = 0.766) also exhibited heterogeneous levels of predictive precision for detecting osteosarcoma." (PMID 40616392, 2025). "In osteosarcoma, the lnc-FGD5-AS1 is upregulated in osteosarcoma cells resistant to doxorubicin, and knockdown of its expression attenuates the chemoresistance to DOX by WNT5A-driven autophagy through miRNA-154-5p sponging." (PMID 38933333, 2024). "In conclusion, ROR2 receptor, acting as the upstream of PI3Kα/Akt/RhoA signaling, is required for Wnt5a-induced the migration, not the proliferation of osteosarcoma cells." (PMID 29213214, 2017). "To answer this question, we quantified WNT5A promoter A and promoter B specific transcript levels in normal osteoblasts, osteosarcoma cell lines, and primary osteosarcoma tumor tissue." (PMID 26978652, 2016). "In murine osteosarcoma cells, FHL2 silencing using shRNA decreased canonical Wnt/β-catenin signaling and reduced the expression of Wnt responsive genes as well as of the key Wnt molecules Wnt5a and Wnt10b." (PMID 23383046, 2013). "Lastly, Wnt5a/ROR2 signaling does not alter the cell proliferation of MG-63 osteosarcoma cells." (PMID 29213214, 2017). "Finally, we find that Wnt5a/ROR2 signaling does not affect the proliferation of osteosarcoma cells." (PMID 29213214, 2017).
rheumatoid arthritis (28 papers, 2006 to 2025). A chronic, systemic autoimmune disorder characterized by inflammation in the synovial membranes and articular surfaces. "Since Wnt5a expression is associated with rheumatoid arthritis and periodontitis, expression of Wnt5a and its cell surface receptors, Frizzled and receptor tyrosine kinase-like orphan receptor 2 (Ror2), were examined." (PMID 26789270, 2016). "Regulation of the Wnt signalingpathwayin rheumatoid arthritis involves interleukin-1 beta,tumor necrosis factor alpha, and interleukin-6, which activatethe expression of the WNT5A gene encoding the WNT5Aprotein – a ligand of FZD receptors participating in the noncanonicalWnt pathway." (PMID 41536794, 2025). "Wnt5a, a ligand of the Wnt-signaling pathway, is also overexpressed in rheumatoid arthritis patients." (PMID 35160258, 2022). "In synoviocytes from rheumatoid arthritis patients, the expressions of Wnt5a and Frizzled5 (Fzd5) were significantly enhanced and their blockades inhibited synoviocyte activation." (PMID 26789270, 2016). "Recently, Wnt5a was highly expressed in synovial tissues in a mouse model of rheumatoid arthritis where inhibition of Wnt5a-Ror2 signaling suppressed bone loss." (PMID 26789270, 2016). "Wnt5a is also upregulated in synovial fibroblasts of inflammatory joints in rheumatoid arthritis where it induces IL6, IL8, and IL15." (PMID 19399181, 2009). "According to the ANDSystem knowledge base,interleukin-1 beta and the WNT5A protein mutually activateeach other’s expression, which may create a vicious cycle inthe pathogenesis of rheumatoid arthritis." (PMID 41536794, 2025). "While previous studies have highlighted TP’s suppression of IL-17A via Th17 inhibition or NF-κB signaling in conditions such as liver fibrosis and rheumatoid arthritis, our work uncovers a previously unrecognized mechanism: TP’s regulation of the Wnt5a/β-catenin axis in keratinocytes." (PMID 40365308, 2025). "Moreover, the utility of Wnt5a in predicting the severity and progression of other inflammatory diseases, such as rheumatoid arthritis, systemic lupus erythematosus, and coronavirus disease-2019, has been evaluated." (PMID 38913943, 2024). "We hypothesized that WNT5A could contribute to the enhanced migration and invasiveness of rheumatoid arthritis fibroblast-like synoviocytes (RA FLS), which is one of the incompletely understood aspects of the RA FLS aggressive phenotype." (PMID 33178184, 2020). "Moreover, Wnt5a overproduction in rheumatoid arthritis was related to the secretion of IL-1β and IL-6 in BMSC." (PMID 24993819, 2014). "On the other hand, WNT5A is highly expressed in synovial tissues in rheumatoid arthritis (RA) patients." (PMID 35052478, 2022). "Wnt5a promotes the expression of inflammatory cytokines in synovial tissue, induces chemokine production, and regulates MMP production, and therefore, is implicated in bone and cartilage degradation and is a promising therapeutic target for rheumatoid arthritis." (PMID 35160258, 2022). "However, it is unclear whether the Wnt5a pathway in the spinal cord plays a role in rheumatoid arthritis pain." (PMID 32399022, 2020). "Fifth, our data show that dermal fibroblasts in psoriasis are strongly positive for Wnt5a and activated fibroblasts from rheumatoid arthritis are synthesize inflammatory cytokines, most notably IL15, subsequent to Wnt5a/Fzd5 signalling." (PMID 19399181, 2009). "However, it is important to note that WNT5A expression may vary in patients with rheumatoid arthritis (RA)." (PMID 40299569, 2025). "In contrast to negative regulators of the canonical Wnt-pathway, aberrant expression of Wnts such as Wnt5a and Wnt7B that activate the non-canonical pathway was observed in the joints of rheumatoid arthritis patients." (PMID 27833613, 2016). "Non-canonical Wnt ligands Wnt5a and Wnt7b were upregulated in the joints of rheumatoid arthritis patients, and the non-canonical Wnt/Ca2+ pathway has been associated with the pathophysiology of psoriasis." (PMID 27833613, 2016).
rheumatoid arthritis (continued). "Genomic studies have shown WNT5A, agonist of FZD receptors, to be up-regulated in T-cells, macrophages and dendritic cells exposed to pathogens as well as in pathologies involving inflammation such as rheumatoid arthritis." (PMID 23717650, 2013). "In bone marrow stromal cells, LPS induces WNT-5A where it regulates expression of a plethora of proinflammatory cytokines in a MAPK- and NFκB-dependent signaling and promotes chemotactic migration of monocytes and T cell indicating a possible role in pathophysiology of rheumatoid arthritis." (PMID 26514730, 2016). "Studies of rheumatoid arthritis have accumulated evidence that Wnt5a-Fz5 mediated signalling can contribute significantly to the production of pro-inflammatory cytokines (IL6, IL8, IL15) and that overexpression of Wnt5a leads to increased pro-inflammatory cytokine levels." (PMID 16438732, 2006). "In a review article of WNT5A signaling, the induced WNT5A activates non-canonical Wnt signaling to regulate the control of tissue polarity and cell aggregation and canonical WNT signaling for the proliferation of human synovial fibroblasts in rheumatoid arthritis (RA)." (PMID 30544699, 2018).
lung fibrosis (26 papers, 2011 to 2025). "Here, we used the bleomycin-induced lung fibrosis model in a conditional gene-deficient mouse, where the Wnt5a gene was excised from SMC." (PMID 34451852, 2021). "Wnt5a signalling is associated with several human pathologies such as pulmonary fibrosis, renal fibrosis, post-infarct cardiac remodelling and hypertrophic scars." (PMID 31890678, 2019). "Here we show that airway smooth muscle cells can contribute to the development of lung fibrosis by expressing Wnt5a." (PMID 34451852, 2021). "We show here for the first time that Wnt5a KO in airway SMC leads to an improved clinical phenotype in a mouse model of bleomycin-induced lung fibrosis." (PMID 34451852, 2021). "In this study, the role of Wnt5a in the development of lung fibrosis was evaluated by inducing lung fibrosis with the cytostatic drug bleomycin in conditional knockout (KO) mice lacking the Wnt5a gene in SMC." (PMID 34451852, 2021). "WNT5a signalling is a regulator of fibroblast proliferation and resistance to apoptosis, both mechanisms involved in the development and progression of lung fibrosis in IPF." (PMID 34947932, 2021). "Wnt5a contributes to pulmonary fibrosis by stimulating the fibroblast proliferation in human lung with usual interstitial pneumonia." (PMID 32552754, 2020). "The same inducible TGF-alpha transgenic mouse line was originally used to study lung fibrosis, suggesting that the pro-fibrotic effect of TGF-alpha was associated with Wnt5a up-regulation." (PMID 30840655, 2019). "In COPD and idiopathic pulmonary fibrosis, pulmonary Wnt5a was almost exclusively secreted by fibroblasts, had pro-fibrotic effects and affected the balance between canonical and non-canonical Wnt signaling." (PMID 28615692, 2017). "Wnt5a has been extensively examined in pulmonary hypertension and in diseases characterized by pulmonary fibrosis, often complicated by pulmonary hypertension and RV dysfunction." (PMID 28615692, 2017). "We recently demonstrated that TGF-β and wingless-type integration site family, member 5A (WNT5A) activation are also important mechanisms involved in lung fibrosis after MV in murine models of acute lung injury and VILI." (PMID 25871971, 2015). "The upregulation of WNT5A is not only restricted to SSc, but is also observed in fibroblasts of patients with sclerodermatous chronic graft-versus-host disease (scl cGvHD) and idiopathic pulmonary fibrosis (IPF)." (PMID 38747285, 2024). "Therefore, this study provides interesting new insights in the role of SMC-derived Wnt5a as a profibrotic factor in lung fibrosis, revealing it as a potential target besides that of TGF-β to modulate the progression of lung fibrosis." (PMID 34451852, 2021). "Intravenously injected MSC-Exos attenuated pulmonary vascular remodeling and lung fibrosis by down-regulating the gene expression of β-catenin, cyclin D1 and TGF-β1 and by enhancing expression of Wnt5a and BMPR2 (Bone Morphogenetic Protein Receptor Type 2)." (PMID 38673961, 2024). "Bioinformatics analysis disclosed that both WNT5A and IL11 were involved in pulmonary fibrosis idiopathic disease and functional assays confirmed their association with profibrotic cell responses." (PMID 37545510, 2023). "Several Wnt Family members such as WNT5A and WNT7B play a role in fibrotic diseases such as idiopathic pulmonary fibrosis and renal fibrosis." (PMID 36421707, 2022). "Dysregulated WNT5a signaling is observed in many lung diseases, ranging from chronic obstructive pulmonary disease (COPD) and idiopathic pulmonary fibrosis (UIP/IPF) to asthma." (PMID 32046118, 2020). "We observed increased expression of WNT5A, cyclin D1, VEGF, and MMP7, all of which are Wnt target gene products that play an important role in pulmonary fibrosis." (PMID 25331176, 2014).